CASC16 (cancer susceptibility 16)
Synonyms: LOC643714; LINC00918
Gene: Long non-coding RNA gene on chromosome 16 (52,552,055 to 52,652,132, reverse strand). Ensembl gene ENSG00000249231.
Diseases named in the same sentence as CASC16 in open-access papers:
CASC16 is named in the same sentence as 5 diseases in open-access papers, as found by Europe PMC text mining. Sharing a sentence is not in itself a finding about the gene and the disease. The quoted sentences say what the papers report.
breast carcinoma (10 papers, 2016 to 2025). "Nevertheless, RNA genes like CASC16 were associated to breast cancer (Section 3.1), reminding us of the importance of using networks beyond coding genes." (PMID 33735170, 2021). "Rs447842227 polymorphism in CASC16 is also a strong current candidate association with breast cancer risk." (PMID 31996122, 2020). "CASC16 rs12922061 and rs4784227 polymorphisms correlated with an increased risk of breast cancer in BMI > 24 kg/m2." (PMID 31996122, 2020). "Rs3803662 was identified SNP in the CASC16 gene association with breast cancer as previously published studies." (PMID 31996122, 2020). "In summary, CASC16 rs4784227 and rs12922061 were significantly related to increased susceptibility to breast cancer." (PMID 31996122, 2020). "In the present case-control study, 681 breast cancer patients and 680 free-cancer subjects were recruited to evaluate the correlation between CASC16 variants and BC risk in a Northwest Chinese female population." (PMID 31996122, 2020). "This investigation aimed to explore the association between CASC16 polymorphisms and breast cancer susceptibility." (PMID 31996122, 2020). "Considerably increased association between rs3803662 in the CASC16 gene and breast cancer was studied in Japanese and Caucasian women." (PMID 31996122, 2020). "Their results provided strong evidence implicating intronic variant rs4784227 on CASC16 gene as a functional variant causing breast cancer at the 16q12.1 locus in Asian women [OR = 1.25, 95% CI = 1.20–1.31, P = 3.2 × 10− 25]." (PMID 29433565, 2018). "The SNPs at 16q12, close to the TOX3 and CASC16 genes, represent one of the susceptibility loci identified by GWAS, showing strong evidence for breast cancer association across various populations." (PMID 27806084, 2016). "The relationship between the rs4784227 polymorphism of CASC16 and the risk of breast cancer." (PMID 36540803, 2022). "Moreover, a recent study published a variant in CASC16 to correlate to breast cancer susceptibility." (PMID 35267517, 2022). "The rs4784227 polymorphism of CASC16 may affect susceptibility to breast cancer and is associated with perineural invasion, menstrual status and histological grade in BC patients." (PMID 36540803, 2022). "The haplotype analysis revealed that Grs45544231 Trs12922061 Ars3112612 and Grs45544231 Crs12922061 Ars3112612 haplotypes in the CASC16 gene were found to reduce risk of breast cancer (OR = 0.82, 95% CI = 0.69–0.98, p = 0.025; OR = 0.85, 95% CI = 0.73–0.99, p = 0.039; respectively)." (PMID 31996122, 2020). "In addition, the CASC16 polymorphisms correlations with breast cancer were carried out in accordance with BMI-based stratification." (PMID 31996122, 2020). "However, the previous studies mainly focused on rs3803662, rs12922061, and rs3112612 polymorphisms in CASC16 association with breast cancer risk in a Southern Chinese population." (PMID 31996122, 2020). "Our study revealed that CASC16 genetic variants were significantly related to breast cancer susceptibility, which might give scientific evidence for exploring the molecular mechanism of breast cancer." (PMID 31996122, 2020). "One study showed that the CASC16 gene had higher expression in breast cancer cells than in normal cells, and some loci of CASC16 have been demonstrated to be significantly associated with BC susceptibility." (PMID 36540803, 2022). "Taken together, these findings suggested an important role for the CASC16 gene in the occurrence of breast cancer." (PMID 31996122, 2020). "Data from one study showed that CASC16 gene had a higher expression in breast cancer cells compared with normal cells." (PMID 31996122, 2020). "In this study, we tested if overexpression of TOX3 is due to epigenetic factors that regulate TOX3/CASC16 expression in breast cancer cells." (PMID 27806084, 2016).
breast carcinoma (continued). "Eight of the breast cancer-associated variants are intronic variants in the TOX3 gene, one is a intronic variant in the CASC16 gene, while the remaining one is located in the intergenic region between TOX3 and CASC16." (PMID 41180965, 2025). "Therefore, next work should focus on exploring the functions of CASC16 in breast cancer." (PMID 31996122, 2020). "Besides, we determined the role of CASC16 SNPs in risk of breast cancer but there were still not detecting function of CASC16 in occurrence and evolution of breast cancer." (PMID 31996122, 2020). "In addition, our results could not confirm that the rs4784227 polymorphism of CASC16 had an effect on the prognosis of breast cancer." (PMID 36540803, 2022).
lymph node metastasis (1 paper, 2020). "We also assessed the effect of CASC16 gene polymorphisms on BC risk by clinical characteristics including clinical stage, tumor size, lymph node metastasis, and BMI." (PMID 31996122, 2020).
cancer (4 papers, 2020 to 2023). A tumor composed of atypical neoplastic, often pleomorphic cells that invade other tissues. "Two SNPs (rs4784227/rs3803662) located in the lncRNA cancer susceptibility 16 (CASC16) have been investigated in BC in different populations, indicating their possible association with BC risk." (PMID 37239331, 2023). "This research was designed to explore the association between the rs4784227 polymorphism of cancer susceptibility candidate gene 16 (CASC16) and BC susceptibility and prognosis, aiming to provide further information for the early detection of BC and to accelerate comprehensive cancer management." (PMID 36540803, 2022). "Cancer susceptibility candidate gene 16 (CASC16), is one of these genes that have been studied." (PMID 36540803, 2022). "Cancer-susceptibility candidate 16 gene (CASC16), also termed LOC643714, is a kind of long non-protein coding RNA and located at chromosome 16q12.1." (PMID 31996122, 2020).
tumor (4 papers, 2012 to 2025). "Meanwhile, we noticed that CASC15, CASC8, CASC9, and CASC19 were highly expressed in tumor samples and CASC16 and CASC18 were lowly expressed in tumor tissues." (PMID 40746360, 2025). "Based on our expression analysis, CASC16 is upregulated in tumor samples (logFC = 1.92) and is specifically upregulated in estrogen-positive subtypes." (PMID 37239331, 2023). "Furthermore, our study firstly revealed that rs45544231 and rs3112612 in CASC16 played protective roles in tumor size > 2 cm individuals." (PMID 31996122, 2020).
CASC16 also shares sentences with these, for which no sentence is quoted: breast and ovarian cancer (1 paper).